DPP4 (dipeptidyl peptidase 4)
Diseases named in the same sentence as DPP4 in open-access papers (continued):
Sharing a sentence is not in itself a finding about the gene and the disease.
Insulin resistance (continued). "Dipeptidyl peptidase-4 (DPP-4, EC 3.4.14.5), also known as CD26, is a novel adipokine that correlates with adipocyte inflammation and insulin resistance." (PMID 38074873, 2023). "Aside from their inhibitory effects on insulin resistance and macrophage activation in NASH, DPP4 inhibitors have been reported to suppress the progression of NASH-related HCC through downregulation of nucleotide production." (PMID 35053615, 2022). "Dipeptidyl peptidase-4 (DPP-4) degrades GLP-1 and mediates insulin resistance by impairing the activation of AKT." (PMID 36352450, 2022). "Another study showed that inhibition of dipeptidyl peptidase 4 (DPP4) skews KCs toward the anti-inflammatory M2 phenotype, thereby alleviating insulin resistance, steatohepatitis, and fibrosis in cholesterol high-fat diet models." (PMID 35656309, 2022). "Dipeptidyl peptidase-4 (DPP4) and progranulin (PGRN) are two novel adipokines related to insulin resistance (IR)." (PMID 35178210, 2022). "Here we demonstrated that the injection of nondiabetic plasma-treated SVFs into the adipose tissue of Leprdb/db mice decreased proinflammatory cytokine expression, suppressed plasma DPP4 activity and CCL2 levels, and ameliorated insulin resistance." (PMID 35883204, 2022). "An increase in GAL4 leads to increased activity of DPP4, which reduces the activity of GLP1, contributing to insulin resistance and DM development." (PMID 34372849, 2021). "These actions of RANKL-induced DPP4 appear to be synergistic with other effects of RANKL on glucose metabolism, which are to induce insulin resistance and increase circulating glucose levels." (PMID 31911667, 2020). "Next to the key role of ADA in T-cell activity and insulin resistance, it is bound on the cell surface by CD26 protein (DPP-4) that is an important modulator of insulin secretion." (PMID 33053898, 2020). "DPP4 and GLP-1 had been found to play important roles in oxidative stress, lipid metabolism, insulin resistance, and inflammation." (PMID 32802136, 2020). "Dipeptidyl peptidase-4 (DPP-4) is released from adipose tissue and acts as a pro-inflammatory adipokine, mediating local inflammation, insulin resistance, and metabolic syndrome." (PMID 32610588, 2020). "Down-regulation of DPP-4 by NL@Cas9-RNP treatment also reconciled glucose tolerance and insulin resistance in a manner similar to sitagliptin." (PMID 30696428, 2019). "It is degraded by enzyme dipeptidyl peptidase-4 (DPP-4), involved in adipose tissue inflammation, which in its way is related to insulin resistance." (PMID 31467596, 2019). "Consequently, we speculated that in a relatively early stage, the various factors of insulin resistance or the components of the metabolic syndrome not only have a close relationship with DPP4 protein level, but they may also be closely related with DPP4 activity." (PMID 24647445, 2014). "Potentially, increased DPP-4 activity in GDM and EGWG may influence the development of inflammation, impair insulin signaling, and, finally, contribute to insulin resistance." (PMID 38339106, 2024). "In comparative analysis, one large observational study found that markers of insulin resistance (including higher HOMA-IR, BMI, fasting triglycerides, and HDL) do not alter GLP1-RA response, but are associated with lesser DPP4-inhibitor response." (PMID 37131814, 2023). "Last, we evaluated DPP4 levels in patients with hepatitis C infection with dysglycemia (Homeostatic Model Assessment of Insulin Resistance > 2) who underwent direct antiviral treatment (with/without ribavirin)." (PMID 36472923, 2023). "(BMI) Body mass index, (DDP-4I) Dipeptidyl peptidase-4 inhibitors, (GLP-1 RA) Glucagon-like peptide-1 receptor agonist, (HOMA-IR) homeostasis model assessment of insulin resistance, (NAFLD) nonalcoholic fatty liver disease, (M) Men and (W) Women, (US) liver ultrasound." (PMID 37081489, 2023).
Insulin resistance (continued). "In terms of the control of blood sugar and reduced insulin resistance, an insulin pump (CSII) combined with biguanide, DPP-4 inhibitors, sensitizers, and GLP-1 receptor agonists can further reduce FPG, 2hPG, and HOMA-IR levels compared with an insulin pump alone." (PMID 36015100, 2022). "It is worth noting that DPP-4 affects insulin resistance cascades, independent of the degradation of GLP-1." (PMID 35290413, 2022). "DPP-4 inhibitors can inhibit glucagon secretion by increasing endogenous GLP-1 in patients and can be used in combination with insulin to improve insulin resistance, eliminate hyperglycemic toxicity altogether, complement the mechanism, and control glucose for a long time." (PMID 36015100, 2022). "Therefore, drugs that are DPP-4 inhibitors delay the breakdown of endogenous incretins GIP and GLP-1 and are successfully used to combat insulin-resistance and DM 2 management." (PMID 35205155, 2022). "Finally, taken together, these data show that DPP4 may negatively affect insulin sensitivity and secretion, favoring mechanisms leading from chronic caloric excess and positive energy balance to body weight gain and development of insulin-resistance-related diseases." (PMID 36140405, 2022). "Fortunately, Gemigliptin, a novel DPP‐4 inhibitor, could efficiently inhibit LECT2 expressions, improve hepatic steatosis and ameliorate insulin resistance by increasing AMPK phosphorylation and reducing CD209 receptor‐mediated JNK pathway." (PMID 35656863, 2022). "OMG might thus block the activity of DPP4 highly secreted from the liver under conditions of NAFLD/NASH, probably averting the promotion of adipose inflammation and insulin resistance in liver." (PMID 33691757, 2021). "Daily doses of DPP4 inhibitors do not result in decreased plasma insulin levels or ameliorated insulin resistance in insulin-resistant, hyperinsulinemic individuals." (PMID 32211075, 2020). "The main components of EGb may act on multiple targets, such as PTGS2, PPARG, DPP4, and GSK3B, to regulate multiple pathways, and play an antiaging role by inhibiting oxidative stress, inhibiting inflammation, and ameliorating insulin resistance." (PMID 32802136, 2020). "In a prospective study from China, DPP4 activity was suggested to be a predictor for the onset of insulin resistance, prediabetes, and T2DM independent of BMI." (PMID 31402899, 2019). "Plasma DPP4 activity positively correlated with chronic hyperglycemia in both type 1 and T2DM patients and served as an important predictor for the onset of insulin resistance both in type 1 diabetes and T2DM." (PMID 31402899, 2019). "For insulin resistance, we found no significant improvement after treatment with DPP-4 inhibitors as monotherapy." (PMID 28322294, 2017). "Similar to the findings for DPP-4 inhibitor monotherapy, we found no significant improvement in insulin resistance after treatment with DPP-4 inhibitors as monotherapy." (PMID 28322294, 2017). "It is well-known that the inflammation was widely identified as a major contributor in the development of insulin resistance (IR) and T2DM, through activation of T-cells that mediate insulin resistance and adipose tissue inflammation, in which DPP4 plays a major role." (PMID 27111895, 2016). "It is believed that metformin treatment is the successful approach to reduce insulin resistance mainly through activation of liver AMPK, whereas DPP-4 inhibitors exhibit the best effects after oral glucose loading, emphasizing the incretin effect after oral stimulation." (PMID 23137106, 2012). "Numerous methods and drugs have been designed to combat insulin resistance, including metformin, thiazolidinediones (TZDs), sodium-glucose cotransporter 2 inhibitors (SGLT2i), glucagon-like peptide 1 receptor agonists (GLP1RA), and dipeptidyl peptidase 4 inhibitors (DPP4i)." (PMID 39873298, 2025).
Insulin resistance (continued). "To determine whether these hormones participate in the insulin‐sensitizing action of SSTR5 inhibition, we evaluated the effects of alogliptin, a dipeptidyl peptidase 4 (DPP4) inhibitor that increases plasma GLP‐1 and insulin levels, on insulin resistance in KK‐Ay mice." (PMID 36585794, 2023). "However, notably, silencing DPP4 expression in hepatocytes suppressed inflammation of VAT and insulin resistance, but DPP4 inhibition by oral inhibitors did not." (PMID 35053615, 2022). "Interestingly, silencing expression of DPP4 on hepatocytes suppressed inflammation of visceral adipose tissue and insulin resistance, but this effect did not occur with sitagliptin, an orally administered DPP4 inhibitor." (PMID 33691757, 2021). "However, daily doses of DPP4 inhibitors do not lower plasma insulin in patients with insulin resistance." (PMID 32211075, 2020). "As oral DPP4 inhibitors do not suppress insulin resistance, the first question is whether this is due to the oral application form or due to the dosage." (PMID 30360455, 2018). "In the meta-analysis of the effects of individual DPP-4 inhibitors on insulin resistance, we observed a significant improvement in insulin resistance with sitagliptin treatment without evidence of significant heterogeneity (WMD −0.38; 95% CI −0.69, −0.08; I2 = 0%, P for heterogeneity = 0.58)." (PMID 28322294, 2017). "However, there was no significant improvement in insulin resistance with the use of DPP-4 inhibitors as monotherapy or as add-on therapy in combination with other drugs." (PMID 28322294, 2017). "Interestingly, our meta-analysis showed that sitagliptin, but not the other tested DPP-4 inhibitors, as monotherapy resulted in significant improvement in insulin resistance." (PMID 28322294, 2017). "However, our study did not explore much about the mechanism by which increase in DPP4 activity lead to insulin resistance, that's why we are still not sure that DPP4 activity can lead to increase in insulin resistance." (PMID 24647445, 2014). "Elevated plasma DPP4 activity in individuals without health conditions is a standalone predictor of the development of metabolic syndrome and might constitute a pivotal link connecting central obesity, insulin resistance, and subsequent CVD." (PMID 40904650, 2025). "Therefore, DPP4 might play a role in the development of adipose inflammation and insulin resistance although there is a lack of direct evidence." (PMID 26075284, 2015). "By contrast, the lack of DPP4 attenuates HFD-induced AT inflammation and insulin resistance and enhances adiponectin levels, despite increases in visceral fat mass." (PMID 35909571, 2022). "Lastly, this study is an epidemiological study and somehow it fails to address the precise role of DPP4 and GLP1 in the pathogenesis of metabolic syndrome and insulin resistance which is needed to be elucidated by further basic investigation." (PMID 24647445, 2014). "Finally, injection of non-diabetic plasma decreased plasma DPP4 activity and CCL2 levels, and ameliorated insulin resistance." (PMID 34043673, 2021). "However, it may not take into account other metabolic (e.g. insulin resistance) and VAT physiological (e.g. adipocyte size, immune cell infiltration) parameters that may better discriminate those expressing DPP4 at greater levels in their VAT." (PMID 23379505, 2013).
Hyperglycemia (192 papers, 2010 to 2026). An increased concentration of glucose in the blood. "Secondly, hyperglycemia can be a confounding factor in the association of DPP-4-inhibitor usage with DPP-4 enzyme activity." (PMID 35893426, 2022). "Hyperglycemia is associated to a significant DPP-4 activity increase only in microvascular endothelial cells." (PMID 21747834, 2011). "This interplay between dysregulated DPP4 and hyperglycemia may contribute to developing NOD in susceptible individuals." (PMID 39205219, 2024). "The literature has shown that DPP-4 inhibitors could improve two important risk factors for diabetic nephropathy, hyperglycaemia and albuminuria." (PMID 39271520, 2024). "As oral antidiabetic drugs, DPP-4 inhibitors may exert their anti-inflammatory effects via a hypoglycemic effect; hyperglycemia has been associated with proinflammatory responses." (PMID 35328486, 2022). "It has also been reported that postprandial hyperglycemia and fluctuation of glucose level, which may cause sympathetic nerve activation, are improved by DPP-4 inhibitors." (PMID 32539832, 2020). "However, chronic hyperglycaemia was significantly associated to an increased DPP-4 activity and mRNA expression in human glomerular endothelial cells in vitro." (PMID 21747834, 2011). "The reduced proteolysis of incretins by bacterial DPP-4 resulted in a decline in blood insulin levels and an increase in postprandial hyperglycemia because incretins increase insulin production from pancreatic cells after food intake." (PMID 40429343, 2025). "Gliptins, or dipeptidyl peptidase-4 (DPP-4) inhibitors, are among the most recently licensed medications for the treatment of hyperglycemia in T2DM patients." (PMID 40430475, 2025). "By breaking down incretin peptides including glucagon-like peptide 1 (GLP-1) and glucose-dependent insulinotropic polypeptide, which stimulate the release of insulin from pancreatic β cells, DPP4 plays a crucial role in regulating postprandial hyperglycemia." (PMID 38337597, 2024). "DPP4/CD26 inhibitors (gliptins) have found application in the treatment of hyperglycaemia since they inhibit the degradation of glucagon-like peptide-1 (GLP-1) and glucose-dependent insulinotropic polypeptide (GIP) hormones." (PMID 39273582, 2024). "Sitagliptin (Januvia) is a type 2 anti-diabetic drug currently in clinical use for the management of hyperglycemia, via dipeptidyl peptidase-4 (DPP-4) inhibition." (PMID 39080769, 2024). "The outcome of a prospective cohort study conducted on the Chinese adult population demonstrated that increased plasma DPP4 activity predicted new-onset hyperglycemia." (PMID 39507187, 2024). "Community-based large-scale studies in the Bangladeshi young population should be conducted to evaluate the role of the DPP-4 enzyme as a prospective circulatory determinant of β cell dysfunction leading to new-onset hyperglycemia." (PMID 39507187, 2024). "As a result of incretins’ ability to increase insulin production from pancreatic β cells following eating, blood insulin levels were lowered, and postprandial hyperglycemia was subsequently enhanced when bacterial DPP-4 restricted the proteolysis of incretins." (PMID 38337597, 2024). "It was also observed that high glucose load significantly enhanced DPP4 mRNA expression in human hepatocyte line HepG2 cells, suggesting that DPP4 expression is directly affected by hyperglycemia." (PMID 39507187, 2024). "Dipeptidyl peptidase-4 (DPP-4) inhibitors like sitagliptin are vital second-line or monotherapy anti-hyperglycemia drugs, decreasing plasma DPP-4 activity by 80% and elevating active glucagon-like peptide-1 levels, thus enhancing cell functionality." (PMID 37809225, 2023). "GLP-1 receptor agonists and dipeptidyl peptidase 4 inhibitors should be considered as second-line treatments in individual cases, having an important role in the treatment of pasireotide-induced hyperglycemia." (PMID 37628857, 2023).
Hyperglycemia (continued). "First, a small dose of a GLP-1RA, in place of the usual dose of a DPP-4 inhibitor, improved glycemic control, including GV and postprandial hyperglycemia." (PMID 35097130, 2022). "Among DPP-4 inhibitor users, those who initially had received more than three different oral anti-hyperglycemia agents had a significant reduction in mean HbA1c after switching to GLP-1 RAs." (PMID 36422091, 2022). "Dipeptidyl peptidase (DPP)-4 inhibitors are a class of drugs prescribed to control hyperglycemia in type 2 diabetes patients." (PMID 36145615, 2022). "The DPP-4 inhibitor user group was more likely to have received more than four different types of oral anti-hyperglycemia agents (74.54%)." (PMID 36422091, 2022). "The excess degradation of GLP-1 and GIP by DPP-4 can be related to the hyperglycemia condition, which can be corrected by blocking the DPP-4 activity." (PMID 35956932, 2022). "Vildagliptin, a dipeptidyl peptidase 4 inhibitor, is an oral hypoglycemic drug that reduces hyperglycemia in T2DM." (PMID 33815116, 2021). "Hyperglycaemia is currently managed with an array of medications such as sulfonylureas, thiazolidinediones, dipeptidyl peptidase-4 inhibitors, GLP-1 analogues, metformin and SGLT2 inhibitors (Keri, Samji & Blumenthal, 2018)." (PMID 33976959, 2021). "DPP4 is a key factor that modulates postprandial hyperglycemia by degrading incretin peptides, i.e., glucagon‐like peptide 1 (GLP‐1) and glucose‐dependent insulinotropic polypeptide (GIP), which induce secretion of insulin from pancreatic β cells." (PMID 33006264, 2021). "Glinides, α-glucosidase inhibitors, and dipeptidyl peptidase 4 (DPP-4) inhibitors are hypoglycemic drugs that decrease postprandial hyperglycemia." (PMID 34439553, 2021). "Anagliptin is a novel compelling and specific inhibitor of dipeptidyl peptidase-4 (DPP-4) first approved for hyperglycemia therapy in Japan in 2012." (PMID 34288819, 2021). "Biguanide antihyperglycemic agent and dipeptidyl peptidase-4 inhibitors were prescribed for one and two cases of hyperglycemia, respectively." (PMID 33711960, 2021). "DPP-4 inhibitors not only ameliorate hyperglycemia, but also improve dyslipidemia with modest blood pressure lowering effects." (PMID 32646003, 2020). "Dipeptidyl peptidase-4 inhibitors (DPP4i) are approved for the treatment of hyperglycemia in patients with T2D." (PMID 32231442, 2020). "This phenomenon provides a rationale for the inhibition of DPP4 to protect the microcirculation from hyperglycemia." (PMID 33050169, 2020). "Hyperglycemia should be managed by initiation of metformin and staged treatment intensification with a dipeptidyl peptidase 4 inhibitor, with a switch to a GLP-1 receptor agonist and initiation of insulin, as required, to achieve and maintain glycemic control." (PMID 33434154, 2020). "We look at recent advances in understanding aerobic glycolysis and possibly the action of DPP4 on incretins resulting in insulin dysregulation and suggest key metabolic pathways involved in hyperglycemia regulation." (PMID 30972338, 2019). "The use of DPP-4 inhibitors was found to significantly improve hemoglobin (Hb)A1c levels and hyperglycemia in patients receiving PD." (PMID 31830041, 2019). "Previous studies have found significant correlations between hyperglycemia and DPP4 activity, BDNF and cognitive impairment, to exclude the possible influences of hyperglycemia on DPP4 activity, BDNF and cognitive function." (PMID 30886577, 2019). "Of specific importance to the hyperglycemia encountered in critically ill patients is the action of DPP4 on incretins, specifically on glucagon-like peptide 1 (GLP-1)." (PMID 30972338, 2019). "Dipeptidyl peptidase-4 (DPP-4) inhibitors (gliptins) are among the most recently approved drugs for the treatment of hyperglycemia in patients with T2DM." (PMID 30619349, 2018).